PLAGL2 (PLAG1 like zinc finger 2)
Diseases named in the same sentence as PLAGL2 in open-access papers (continued):
Sharing a sentence is not in itself a finding about the gene and the disease.
cancer (27 papers, 2013 to 2025). A tumor composed of atypical neoplastic, often pleomorphic cells that invade other tissues. "Previous studies have revealed that overexpression of PLAGL2 is associated with many human cancers." (PMID 27537362, 2016). "PLAGL2 is also identified as a prognostic marker, correlating with advanced cancer stages and poor outcomes." (PMID 40773107, 2025). "The related parameters predicted that PLAGL2 is involved in the progression and prognosis of cancer." (PMID 35222518, 2021). "The results showed that PLAGL2 was upregulated in several cancers, including adrenal gland, brain, breast, cervix, colon, esophagus, liver, lung, oral, ovary, and skin." (PMID 35222518, 2021). "The cases were divided into high or low PLAGL2 expression group by the median of PLAGL2 immunostaining score in cancer tissues (n = 92 for each group)." (PMID 35222518, 2021). "Previous studies showed that PLAGL2 can elevate Wnt/β‐catenin signaling in some type of human cancers." (PMID 33634974, 2021). "Our findings were identical with previous results, suggesting that PLAGL2 expression changes in different cancers." (PMID 35222518, 2021). "To explore the pan-cancer correlation between PLAGL2 expression and immune infiltration, we first evaluated the abundance of immune cell infiltration." (PMID 35222518, 2021). "Cumulative studies have suggested that PLAGL2 expression has a vital role in the malignancy of various cancers." (PMID 35222518, 2021). "Subsequent in vitro and in vivo experiments showed that overexpression of PLAGL2 significantly promotes cancer cell proliferation and metastasis, indicating the carcinogenic role of PLAGL2 in regulating GC progression." (PMID 33391500, 2021). "Two members in the family, PLAG1 and PLAGL2, were found to be cell growth promoting and oncogenic in several cancer cell types." (PMID 32087738, 2020). "miR-449a, miR-486-5p and let-7 were found to target the 3’UTR of PLAGL2 mRNA in other cancer cell types." (PMID 32087738, 2020). "PLAGL2, a well-known transcription factor, has been proposed to participate in the physiological regulation of different types of cancers." (PMID 32413870, 2020). "A member of the PLAG gene family, PLAGL2, a zinc finger protein, is unregulated and plays an oncogenic role in several malignant tumors, such as breast cancer and bladder cancer." (PMID 32413870, 2020). "Wnt6 is a gene in the Wnt/β-catenin pathway that can be activated through Plagl2 and can promote cancer development in CRC." (PMID 33396408, 2020). "PLAGL2, a well-known transcription factor, was proposed to participate in the physiological regulation of different types of cells, including cancer cells." (PMID 30305607, 2018). "Previous studies have reported that transcription factor PLAGL2 was increased in a variety of cancers and promoted cancer cells' proliferation and metastasis." (PMID 30305607, 2018). "Whereafter, accumulating studies discovered that PLAGL2 is overexpressed in multiple cancers and plays a critical role in cancer progression." (PMID 30305607, 2018). "Plagl2 is similarly amplified in a number of cancers, including glioblastomas and acute myeloid leukemia." (PMID 30361413, 2018). "The PLAGL2 transcription factor is present, an expressed suppressor of differentiation of stem cells and of stem cancer glial cells." (PMID 28031533, 2017). "The limited number of studies analyzing molecular mechanisms of PLAGL2 suggested that PLAGL2 was expressed distinctly in different cancers, and it probably had tissue specificity." (PMID 27537362, 2016). "The mRNA levels of PLAGL2 in cancer tissues were in contrast with that in normal tissues." (PMID 35222518, 2021). "PLAGL2 mRNA levels in cancer tissues were analyzed using the TIMER and Gent2 databases." (PMID 35222518, 2021).
cancer (continued). "Enhanced PLAGL2 expression was observed in several malignant tumours." (PMID 31827238, 2020). "Given the significant inverse association between ZEB1 and E-cadherin across various carcinomas, we also wondered whether ZEB1 was involved in PLAGL2-induced EMT." (PMID 31827238, 2020). "An aberrant expression of PLAGL2 may be involved in the process of diverse cancer types." (PMID 35222518, 2021). "Both PLAG1 and PLAGL2 overexpression in cultured cells triggers IGF2 gene expression and induces cancer-promoting effects, including transformation." (PMID 37371750, 2023). "Rationale: PLAGL2 (pleomorphic adenoma gene like-2), a zinc finger PLAG transcription factor, is aberrantly expressed in several malignant tumors." (PMID 33391500, 2021). "An analysis of PLAGL2 mRNA levels with cancer and normal tissues in the TIMER and Gent2 databases showed that PLAGL2 expression was critically upregulated in most cancers." (PMID 35222518, 2021). "We further analyzed the expression of PLAGL2 in 15 paired HCC and non‐carcinoma tissues via western blot analysis." (PMID 34586726, 2021). "Additional transcriptional targets of PLAGL2 (e.g., MPL and ASCL2) were found in other cancer cell types." (PMID 32087738, 2020). "The expression level of PLAGL2 in the CRC tissues we collected was also measured; as expected, the level of PLAGL2 was obviously higher in the cancer tissues than in the normal tissues." (PMID 32413870, 2020). "This, along with the presence of a CpG island in the intergenic region between POFUT1 and PLAGL2, indicates that DNA methylation and histone modifications may influence POFUT1 dysregulation in cancer." (PMID 40773107, 2025). "Also, it has been proved that PLAGL2-EGFR-HIF1/2A signaling pathway promotes the progression of HCC and affects the response of cancer cells to anti-EGFR drug erlotinib." (PMID 35692750, 2022). "In addition, PLAGL2 and POFUT1, which are separated by shortest physical sequence distance (<150bp) and exhibit co-expression characteristics in 14 cancer types were used for further analysis." (PMID 29108255, 2017). "It's remarkable that the function of V-ATPases in cancer was closely related to the wnt and notch signaling pathway, which indicateds to us that PLAGL2, POFUT1and TM9SF4 may cooperatively participated in the development human cancer." (PMID 29108255, 2017). "Levels of HMGA1, HMGA2, PLAGL2, IGF2BP2, E2F5, and ARID3A transcripts were also inversely proportional to levels of Let-7 miRNA by examination of a cohort of 199 CRC patients from the TCGA Pan-Cancer analysis project." (PMID 26244988, 2015). "Given the demonstrated oncogenic relevance of MYCN in many types of cancers, whether the PLAGL2-MYCN axis is also a key player in modulating cell differentiation and proliferation in other cancer types is certainly an interesting question to address in the future." (PMID 32087738, 2020).
CNS tumor (5 papers, 2022 to 2025). "By t-SNE dimensionality reduction of DNA methylation profiles, PLAG1-fused tumors show a methylation pattern closely related to the one characteristic of PLAGL1- and PLAGL2-amplified tumors, but otherwise epigenetically distinct from all other described CNS tumor types." (PMID 40751809, 2025). "The recently described entity “CNS tumor with PLAGL amplification” (particularly PLAGL2 in infants and toddlers) also shows overlapping embryonal features with the tumors in this series, nonetheless with a different immune-profile—OLIG2 being mostly negative, and synaptophysin being patchy and weak." (PMID 38500181, 2024). "Through our screening, we identified a subset of CNS tumors (n=12) epigenetically distinct from other known CNS tumor types, but clustering close to the PLAGL1- and PLAGL2-amplified ET, PLAGL subtypes in our t-SNE analysis." (PMID 40751809, 2025). "In keeping herewith, we show through ChIP-seq data that components of the Wnt-pathway such as FZD2 and FZD9 are direct targets of PLAGL1 and PLAGL2 and are overexpressed in the PLAGL1/2-amplified samples compared to the other CNS tumor types." (PMID 36437415, 2023). "We describe a biologically distinct pediatric CNS tumor type (n = 31 cases) that is characterized by focal high-level amplification and resultant overexpression of either PLAGL1 or PLAGL2, and an absence of recurrent genetic alterations characteristic of other pediatric CNS tumor types." (PMID 36437415, 2023).
PLAGL2 also shares sentences with these, for which no sentence is quoted: Neuroepithelial tumors (3 papers); lymphoma (2); malignant glioma (2); astrocytoma (1); colorectal tumor (1); ganglioglioma (1); Hodgkins lymphoma (1); iron deficiency (1); lipoblastoma (1); medulloblastoma (1); oral squamous cell carcinoma (1); pancreatic cancer (1); papillary thyroid carcinoma (1); pilocytic astrocytoma (1); thyroid cancer (1); wasting syndrome (1).